EPO (erythropoietin)
Diseases named in the same sentence as EPO in open-access papers (continued):
Sharing a sentence is not in itself a finding about the gene and the disease.
necrotizing enterocolitis (5 papers, 2015 to 2024). Necrotizing enterocolitis (NEC) is a devastating disease that affects mostly the intestine of premature infants. "Moreover, EPO’s protective role against necrotizing enterocolitis in newborn rats, through inhibiting the formation of nitric oxide, has been demonstrated." (PMID 39338226, 2024). "A previous meta-analysis has also showed that that prophylactic EPO improves cognitive development and early EPO treatment may decrease the rates of necrotizing enterocolitis as well as brain complications, including IVH and periventricular leukomalacia." (PMID 33043002, 2020).
Opportunistic infection (5 papers, 2007 to 2025). An infection that is caused by a pathogen that would generally not be able to cause an infection in a host with a normal immune system. "It explores the multifactorial pathophysiology, including direct viral effects on the bone marrow, drug-induced cytopenias, opportunistic infections, nutritional deficiencies, and CHF-related impairments in erythropoietin and thrombopoietin production." (PMID 40901202, 2025).
osteonecrosis (5 papers, 2014 to 2023). A none disease characterized by death of bone tissue due to a lack of blood supply. "Furthermore, erythropoietin also can prevent bone loss in mouse models of osteonecrosis of the femoral head by regulating osteogenesis, angiogenesis, and cell apoptosis." (PMID 35154510, 2022). "Significantly more rats in the Dex group (9 of 10) developed osteonecrosis compared to only 5 in the EPO + Dex group." (PMID 37978375, 2023). "In an experimental model of osteonecrosis of the femoral head, increased expression of Runx2 and osteocalcin was observed both four and eight weeks after EPO treatment." (PMID 37374263, 2023). "The higher VEGF intensity score in the ZA+Pre-PostEPO group compared to the control indicated that EPO can prevent ZA-induced osteonecrosis in the extraction socket by inducing VEGF." (PMID 37374263, 2023). "It is thought that systemic EPO treatment could both prevent osteonecrosis in the jawbone and help treat existing osteonecrosis cases." (PMID 37374263, 2023). "The HIF signaling pathway has also been shown to be important in EPO-stimulated repair of osteonecrosis in rat models, as EPO administration increased the expression of alkaline phosphatase, HIF-1α, runt-related transcription factor 2, and vascular endothelial growth factor." (PMID 33330462, 2020). "The results from the present study demonstrate that EPO exerts prominent protective effects against glucocorticoid-induced osteonecrosis of the femoral head in rats by inhibiting the apoptosis of osteoblasts and osteocytes and increasing the expression of VEGF." (PMID 24503957, 2014).
pulmonary fibrosis (5 papers, 2013 to 2024). Chronic progressive interstitial lung disorder characterized by the replacement of the lung tissue by connective tissue, leading to progressive dyspnea, respiratory failure, or right heart failure. "It is obvious that, due to EPO’s multiple properties, further research is needed to fully elucidate the underlying mechanisms of its protective action in pulmonary fibrosis, as well as to clarify whether it might be a powerful solution against this fatal disease in the future." (PMID 39338226, 2024). "In this study, we investigate the specific anti-inflammatory, antioxidant and antiapoptotic effects of erythropoietin on lung tissue in a bleomycin-induced rat model of idiopathic pulmonary fibrosis." (PMID 39338226, 2024). "This is the first study to demonstrate that erythropoietin impeded pulmonary fibrosis by improving the extent of tissue damage and reducing oxidative load and apoptosis." (PMID 39338226, 2024). "In summary, in this pilot study, EPO promises to help identify hypoxemia early and respond to oxygen treatment, except in pulmonary fibrosis that tends to worsen." (PMID 34068590, 2021). "We posit that triple therapy suppressed lung fibrosis more effectively than monotherapy since the different mechanisms of action of pirfenidone, edaravone and erythropoietin concurrently slowed the progression of lung fibrosis." (PMID 24223628, 2013). "Our results may constitute a starting point for more research on the impact of erythropoietin on pulmonary fibrosis." (PMID 39338226, 2024). "There have been no previous reports on the role of EPO in association with Cyt-C expression in lung fibrosis models." (PMID 39338226, 2024). "In pulmonary fibrosis, HIF-1α, EPO, and VEGF increased with oxygen therapy, which is likely linked to the disease’s pathogenesis and clinical course rather than hypoxemia." (PMID 34068590, 2021). "In pulmonary fibrosis, HIF-1α, EPO, and VEGF increased with oxygen therapy, which is likely more linked to the disease’s pathogenesis and course than to hypoxemia." (PMID 34068590, 2021). "Although there have been no reports in lung fibrosis models concerning the relationship between EPO and i-NOS expression, it has been demonstrated in several studies that the inhibition of i-NOS results in resistance to bleomycin-induced lung injury in mice." (PMID 39338226, 2024). "The pathological lesions that characterize pulmonary fibrosis appeared to be more limited and localized in EPO-treated animals compared to those with no treatment." (PMID 39338226, 2024). "In the previous study, we showed that bone‐derived MSCs in combination with erythropoietin (EPO) can significantly reduce the newborn mice alveolar injury and lung fibrosis induced by high oxygen than MSCs therapy alone, but the transplant timing has not been reported." (PMID 30160360, 2018).
Zinc deficiency (5 papers, 2015 to 2023). A deficiency of the essential metal Zinc; an essential cofactor for many enzymes. "A zinc deficiency causes reductions in erythroid precursors in the bone marrow and in plasma erythropoietin." (PMID 36678192, 2023). "The prevalence of zinc deficiency is extremely high in HD patients, and zinc supplementation reduces the dosage of erythropoietin." (PMID 33863297, 2021). "It has been shown that, in animal studies with mice and rats with zinc deficiency, bone marrow erythrocyte progenitors and plasma erythropoietin levels are decreased." (PMID 27211046, 2016). "In this study, we investigated the effects of zinc supplementation in HD patients with zinc deficiency on changes in the erythropoietin responsiveness index (ERI) by evaluating changes in the levels of hemoglobin, zinc, iron, ferritin, and ESA dosage." (PMID 25988769, 2015). "This study investigated the effects of zinc supplementation in HD patients with zinc deficiency on changes in the erythropoietin responsiveness index (ERI)." (PMID 25988769, 2015).
amyloidosis (4 papers, 2017 to 2024). A disorder characterized by the localized or diffuse accumulation of amyloid protein in various anatomic sites. "Given that amyloid and tau pathology are characteristics of AD, the effects of cTfRMAb-EPO were studied in a tauopathy mouse model (PS19)." (PMID 37111315, 2023). "In addition, both IL-1β and IL-6 are also known as key mediators in chronic inflammation and are associated with long-term hemodialysis complications such as erythropoietin hyporesponsiveness, cardiovascular morbidities and amyloidosis-related bone disease." (PMID 29069222, 2017). "We previously showed that cTfRMAb-EPO is protective in a mouse model of amyloidosis, but its effects on tauopathy are not known." (PMID 37111315, 2023).
anterior ischemic optic neuropathy (4 papers, 2009 to 2023). Anterior ischemic optic neuropathy (AION) is an eye disease characterized by infarction of the optic disk leading to vision loss. "Given its neurotrophic properties, EPO may be an ideal candidate to signal retinal ganglion cells or photoreceptors in anterior ischemic optic neuropathy or central retinal artery occlusion where there are currently no effective treatments." (PMID 19930719, 2009).
autoimmune hemolytic anemia (4 papers, 2022 to 2025). Autoimmune hemolytic anemia (AIHA) is an autoimmune disorder in which various types of auto-antibodies are directed against red blood cells causing their survival to be shortened and resulting in hemolytic anemia. "Interestingly, the role of the three anti-eryptotic factors, erythropoietin, NO synthase, and NFκB, has been investigated in clinical settings, i.e., in autoimmune hemolytic anemia and in obesity." (PMID 35159312, 2022). "Further studies revealed that erythropoietin protects erythrocytes against oxidative stress, and the hormone may be useful for the treatment of patients suffering from decompensated autoimmune hemolytic anemia." (PMID 35159312, 2022). "However, since eryptosis may require specific therapy, as we have already shown by use of erythropoietin, it is recommendable to determine eryptotic cells in IgM warm autoimmune hemolytic anemia (AIHA) or cold agglutinin disease (CAD)." (PMID 36817469, 2023).
autoimmune neuropathy (4 papers, 2011 to 2023). An autoimmune form of peripheral neuropathy. "Thus, EPO ameliorates the clinical signs of autoimmune neuropathy even when therapy was started at later time points, although early treatment has a more prominent effect on disease severity." (PMID 22043313, 2011).
Autoimmunity (4 papers, 2015 to 2024). The occurrence of an immune reaction against the organism's own cells or tissues. "Few APECED patients have been reported in literature with this associated autoimmune disorder due to the presence of autoantibodies against erythroid cells or erythropoietin." (PMID 34078422, 2021). "In the next section, we will explore the homeostatic role of this mechanism of EPO-mediated autoimmunity." (PMID 38191841, 2024). "The control of RBC lifespan by EPO and autoimmunity emerges as a key mechanism in the homeostasis of RBCs." (PMID 38191841, 2024). "Even when using an endogenous gene such as erythropoietin (EPO), some macaques receiving EPO-encoding AAV intramuscularly developed severe autoimmunity against the protein." (PMID 30334070, 2019). "We suggest that EPO could also regulate RBC lifespan through its effects on CD47 and SIRP-α expression and through EPO-induced autoimmunity." (PMID 38191841, 2024). "The effect of EPO on CD47 and SIRP-α would also lead to changes in the autoimmunity threshold." (PMID 38191841, 2024).
autonomic neuropathy (4 papers, 2014 to 2023). An inherited or acquired peripheral neuropathy affecting the autonomic nervous system. "Chronic hyperglycemia causes oxidative stress, autonomic neuropathy, and sympathetic denervation, leading to renal hypoxia and, finally, a reduction in erythropoietin production." (PMID 37109325, 2023). "Autonomic neuropathy can decrease sympathetic stimulation of erythropoietin production through renal denervation." (PMID 25695026, 2014).
brain tumor (4 papers, 2017 to 2023). "For example, a study has found that HIF1α promotes EPO expression at the transcriptional level under hypoxia and achieves antitumor effects by regulating Epo-activated signaling pathways as interfering with the cell cycle of brain tumors." (PMID 35860430, 2022). "The main target of this study was to assess the circulating serum hypoxia biomarkers HIF-1α, VEGF, osteopontin, erythropoietin, caveolin-1, GLUT-1, and LDH pre- and post-radiotherapy in patients with brain tumors." (PMID 36121548, 2022). "The aim was to assess the serum hypoxia biomarkers HIF-1α, VEGF, osteopontin, erythropoietin, caveolin-1, GLUT-1, and LDH pre- and post-radiotherapy in patients with brain tumors." (PMID 36121548, 2022). "For instance, in brain tumor cell lines, ARNT2 can form functional HIF complexes by co-binding with other factors controlling hypoxic responses of the human EPO enhancer." (PMID 29033978, 2017).
Cachexia (4 papers, 2015 to 2022). Severe weight loss, wasting of muscle, loss of appetite, and general debility related to a chronic disease. "Patients with resistance to EPO had a vector pattern indicating a trend to cachexia (p < NS), while patients who responded to treatment had a normal vector pattern." (PMID 31412807, 2019).
fibrosis (4 papers, 2016 to 2024). the formation of excess fibrous connective tissue in an organ or tissue in a reparative or reactive process. "Although limited data are available regarding the effects of EPO on bleomycin-induced fibrosis models, similar findings concerning its protective role on lung tissue injury have been reported in previous studies." (PMID 39338226, 2024).
hydronephrosis (4 papers, 2016 to 2024). Collection of urine in the renal pelvis that results in dilatation of the renal pelvis and calyces. "Further studies are required to elucidate the mechanism and implications of elevated erythropoietin production in hydronephrosis." (PMID 36890599, 2023). "The E-cadherin expression together with the renin and erythropoietin gene expression revealed its functionality, while histological mature glomeruli and hydronephrosis proved the new kidneys’ excretory function." (PMID 35683456, 2022). "Additionally, the link between hydronephrosis and increased EPO production is not well established." (PMID 39767963, 2024).
leukocytosis (4 papers, 2021 to 2025). "Indeed, the compound significantly reduced EPO-induced leukocytosis, reticulocytosis, extramedullary erythropoiesis, and vascular occlusions in the lungs." (PMID 36719747, 2023).
limb ischemia (4 papers, 2010 to 2021). A ischemia that involves the limb. "Briefly, repeated transient limb ischemia rapidly induces renal HIF1α expression, leading to EPO production and release from the kidney." (PMID 34292971, 2021). "In this study, we used an experimental critical limb ischemia (CLI) rat model to reveal the underlying mechanisms and directly examine the benefits of the anti-apoptotic capacity of EPO in the acute phase of limb ischemia and following blood flow recovery." (PMID 27274711, 2016).
macrocytic anemia (4 papers, 2016 to 2023). Anemia that is characterized by increased red blood cell volume. "However, adults exhibited mild macrocytic anemia coincident with subtle perturbation particularly of bone marrow erythropoiesis, with EPO-induced erythropoiesis blunted in the bone marrow of KO mice but enhanced in the spleen." (PMID 37892192, 2023). "We suggest macrocytic anemia without clear etiology with elevated EPO level should be suspected of bone marrow disease in elderly patients." (PMID 37741889, 2023).
meningioma (4 papers, 2021 to 2025). A generally slow growing tumor attached to the dura mater. "Statistical analysis of data revealed a significant increase in serum EPO in meningioma patients either before or after RT when compared to healthy volunteers (p1 < 0.001 and < 0.001, respectively)." (PMID 36121548, 2022).
metabolic acidosis (4 papers, 2014 to 2021). "Metabolic acidosis, ongoing inflammatory process, treatment with erythropoietin and high serum concentrations of calcium and phosphorus have been reported as factors contributing to the development of NSF." (PMID 33804005, 2021).
microcephaly (4 papers, 2015 to 2024). A congenital or acquired developmental disorder in which the circumference of the head is smaller than normal for the person's age and sex. "Among preterm newborns, elevated concentrations of endogenous EPO have been associated with elevated inflammation-related proteins and with a higher risk of lower Mental and/or Psychomotor Development Indices and microcephaly at 2 years." (PMID 34077474, 2021). "Children with hyperEPO were more than twice as likely as those with lower EPO concentrations to have very low (< 55) MDIs and/or PDIs, or microcephaly at age two years." (PMID 25793991, 2015).
normocytic anemia (4 papers, 2014 to 2026). Anemia in which the red blood cell volume is normal. "Normocytic anemia may be caused by inadequate erythropoietin (EPO) levels or decreased erythropoietin response, reduced erythrocyte survival, and bone marrow infiltration." (PMID 33668657, 2021). "We found that in patients with macrocytic and normocytic anemia, the level of erythropoietin (EPO) was positively correlated with soluble transferrin receptor (STFR)." (PMID 42136851, 2026). "It is characterized by normocytic anemia that results from several mechanisms, including dysregulated iron homeostasis, blunted erythropoietin production, erythropoietin resistance, and reduced red blood cell life span." (PMID 35795334, 2022). "A number of medications have been implicated in inducing PRES, including erythropoietin, which is commonly prescribed to ESRD patients to treat the associated normocytic anemia." (PMID 24411012, 2014).
Parkinsonism (4 papers, 2018 to 2024). Characteristic neurologic anomaly resulting from degeneration of dopamine-generating cells in the substantia nigra, a region of the midbrain, characterized clinically by shaking, rigidity, slowness of movement and difficulty with walking and gait. "EPO administration could rescue the expression of TH in rats in which parkinsonism was induced with rotenone or 6-hydroxydopamine, together with decreased levels of tumor necrosis factor alpha in the same brain areas affected by PD." (PMID 33467745, 2021).
peritonitis (4 papers, 2016 to 2025). Inflammation of the peritoneum (tissue that lines the abdominal wall and covers most of the organs in the abdomen). "Both groups had similar clinical characteristics except significantly higher levels of BP, serum calcium, serum parathyroid hormone, peritonitis episodes, and less use of erythropoietin-stimulating agent in the App group." (PMID 40397925, 2025). "As EPOR was mainly detected in macrophages during the self-limited E. coli peritonitis, we next sought to investigate the role of macrophage EPO signaling in infection resolution." (PMID 33927725, 2021). "To determine the major contributions of neutrophils to tissue hypoxia and EPO upregulation at the early time point (6 h) during acute peritonitis, we depleted neutrophils in WT mice using an anti-Ly6G antibody." (PMID 27397585, 2016). "Our findings here have revealed a previously unappreciated effect of macrophage EPO signalling on inflammation resolution in peritonitis." (PMID 27397585, 2016). "We have identified a novel physiological pathway that inducing macrophage EPO signalling to promote inflammation resolution in zymA-induced peritonitis." (PMID 27397585, 2016). "Because EPOR was mainly expressed in macrophages during acute peritonitis, we next sought to investigate the role of macrophage EPO signalling in inflammation resolution." (PMID 27397585, 2016). "Moreover, recently we have shown that EPO enhanced macrophage clearance of apoptotic cells can promote inflammation resolution in sterile peritonitis." (PMID 33927725, 2021). "However, PPARγ upregulation in macrophages was significantly decreased in EPOR-MKO and CGD mice during zymA-induced peritonitis, indicating potential regulation by EPO signalling." (PMID 27397585, 2016). "We also found that EPO-promoted inflammation resolution via PPARγ induction in macrophages, which is consistent with previous work demonstrating that PPARγ activation normalizes peritonitis resolution in CGD mice." (PMID 27397585, 2016). "Thus, we sought to explore whether EPO regulates macrophage efflux to draining lymph nodes during acute peritonitis." (PMID 27397585, 2016). "Levels of peritoneal EPO and macrophage erythropoietin receptor (EPOR) were elevated in self-limited E. coli-initiated peritonitis." (PMID 33927725, 2021). "Our results demonstrated that EPO and EPOR expression is induced in zymA-induced peritonitis." (PMID 27397585, 2016). "During acute peritonitis, PPARγ agonist treatment increased macrophage phagocytosis of ANs in EPOR-MKO mice; however, EPO did not enhance this process during acute peritonitis in PPARγ-MKO mice, demonstrating the important contribution of PPARγ to mediating EPO-promoted efferocytosis." (PMID 27397585, 2016).